BRCA2 (BRCA2 DNA repair associated)
Diseases named in the same sentence as BRCA2 in open-access papers (continued):
Sharing a sentence is not in itself a finding about the gene and the disease.
cancer (continued). "TNF, BRCA2, MYC, and IL6 are some examples of proteins that are frequently associated with PCa and are also known to function as biomarkers for other types of cancer." (PMID 34771740, 2021). "In addition, the breast cancer susceptibility protein, BRCA2, interacts with PLEC, where the BRCA2/PLEC complex is involved in nuclear duplication and centrosome formation." (PMID 34001250, 2021). "As such, they are not suited for integration in the clinical management of patients suffering from progressing cancer, in whom a variant of unknown significance (VUS) in a homologous recombination gene, such as BRCA1 or BRCA2, is discovered." (PMID 34206535, 2021). "We propose that DDX11 provides a mechanism of replication stress tolerance, which sustains survival of cancers, including BRCA1- and BRCA2-deficient cells, and can be exploited therapeutically through the development of specific inhibitors of DDX11 helicase activity." (PMID 33879618, 2021). "In particular, tumors with BRCA2 pathogenic variants associated with defective HR are sensitive to Poly(ADP ribose) polymerase inhibitors, the efficacy of which is mediated through synthetic lethality with BRCA2 loss-of-function in cancer cells." (PMID 34356684, 2021). "Patients with first cancer diagnosis and survivors of some cancers may be screened for genetic risk factors such as MMR and BRCA1/BRCA2 mutations." (PMID 34556087, 2021). "In addition, pan-cancer studies provide evidence for factors affecting predisposition to different cancer types, highlighting rare germline cancer susceptibility variants that affect tumour suppressor genes including ATM, BRCA1, BRCA2, BRIP1, and PALB24." (PMID 34253785, 2021). "The use of PRS in stratifying cancer risk in carriers of high-risk variants in BRCA1, BRCA2, or other genes, may soon become available for clinical use." (PMID 33762893, 2021). "Of the 26 BRCA2-cancer affected men, only 3 underwent prophylactic mastectomy." (PMID 34575694, 2021). "In the context of BRCA1- and BRCA2-derived cancers, other genes involved in high-volume DNA repair, or those key in other critical pathways whose functionality is required for cell survival and proliferation, are potential contenders for BRCA1/2 synthetic lethal partners." (PMID 34070674, 2021). "As FANCI plays a role in FA-HR pathway it may be associated with phenotypically similar cancer families that have implicated BRCA1 and BRCA2." (PMID 34861889, 2021). "Individuals with biallelic BRCA2 pathogenic variants usually suffer from a severe form of FA characterized by BMF, multiple congenital defects, and severe cancer predisposition as patients develop leukemia and/or multiple solid tumors (mainly Wilms and brain tumors) in the first decade of life." (PMID 34504103, 2021). "Given the intimate functional links between PALB2 and BRCA2 and the similar phenotypes associated with biallelic mutations in the genes that encode them, it is plausible that monoallelic PALB2 mutations confer susceptibility to adult cancer." (PMID 33419454, 2021). "Interestingly, this new combination strategy is likely more effective in BRCA2 deficient and BRCA proficient cancers than BRCA1-related cancers." (PMID 33589588, 2021). "There was an increased carrier frequency of FANCI c.1813C>T in BRCA1 and BRCA2 pathogenic variant negative OC families, when including the discovery family, compared to cancer-free females (3/23, 13%; OR = 5.8; 95%CI = 1.7–19; P = 0.005)." (PMID 34861889, 2021).
cancer (continued). "In addition to impairing DNA repair, PARP1/PARP2 inhibitors—which are in clinical use against a growing list of cancers—trap the abundant PARP1 protein on DNA breaks, which has genotoxic cytotoxic consequences, especially in BRCA1- or BRCA2-deficient cancers." (PMID 34210965, 2021). "However, these CRC cells also contain mutations in other cancer related genes (HCT116: KRAS, PIK3CA, CTNNB1, BRCA2, CDKN2A etc.; SW480 or SW620: KRAS and APC etc.), which constitute a unique pathological context in every CRC cell." (PMID 32388500, 2020). "The study defines features useful for identifying BRCA1- or BRCA2-deficient cancer types regardless of subtype." (PMID 32719318, 2020). "In a follow-up study devoted to target validation and further mechanistic insights into CuET effects, we explored the reported exceptional sensitivity to DSF of human cancer cell lines defective in BRCA1 or BRCA2 tumor suppressors, key components of the genome integrity maintenance machinery." (PMID 32085572, 2020). "On the other hand, BRCA2 correlated with CD44 in both types of cancer." (PMID 32610620, 2020). "One 38-year-old male participant with a normal colonoscopy and no self-reported family history of cancer harbored a pathogenic BRCA2 frameshift mutation." (PMID 33260537, 2020). "Our findings suggest that the BRCA2 protein could have a role in protecting the epithelial tissue of the breast against cancer-promoting effects of ovarian hormones." (PMID 32939053, 2020). "Analysis of affected individuals belonging to high‐risk pedigrees has long been a powerful design for identification of rare cancer predisposition genes and variants in Utah (e.g., BRCA1 [OMIM 113705], BRCA2 [OMIM 600185], CDKN2A [OMIM 600160], GOLM1 [OMIM 606804], APC, PTEN [OMIM 601728])." (PMID 33118316, 2020). "The BRCA1 and BRCA2 genes encode proteins involved in double-stranded DNA break repair; thus, BRCA mutation-associated cancers may be more sensitive to chemotherapeutic agents that cause DNA damage, such as platinum-based agents." (PMID 32098267, 2020). "However, characteristics of cancers detected in BRCA2 carriers differ significantly from those detected in BRCA1 carriers." (PMID 32333294, 2020). "Therefore, the defective FA pathway leads to cancer predisposition through genetic instability, such as BRCA1 and BRCA2 dysfunction." (PMID 32269964, 2020). "Nevertheless, studies conducted in patients with PCa have found that more than 30% of patients with germline mutations in DNA repair genes (and 15% of those with the BRCA2 mutation) do not have any family members diagnosed with cancer." (PMID 32545454, 2020). "Interestingly, we find that deep somatic deletions do frequently contribute to biallelic loss of BRCA2 or RAD51C, occurring in 10% of CHORD-HRD patients pan-cancer." (PMID 33149131, 2020). "IBR120 is an inhibitor that disrupts RAD51 interaction with BRCA2 sensitizing cancer cells to IR." (PMID 32932697, 2020). "With regard to cancer, one can speculate autophagy mitigates genomic damage by enabling the translation of Brca2, thereby suppressing early tumorigenesis." (PMID 32681145, 2020). "We also had limited information on treatment and in particular, endocrine therapy which is known to decrease the risk of contralateral cancer and could account for the lower rates in BRCA2 PV carriers who more frequently had ER-positive cancers." (PMID 32045981, 2020). "In relation to tumorigenesis specifically related to BRCA1 and BRCA2, data suggest that BRCA bi-allelic inactivation renders the cell vulnerable to genomic instability, being the background for successive mutations that culminate in cancer development." (PMID 32481735, 2020). "It has been shown that BRCA1 and BRCA2 are involved in the repair process of DNA damage in different tissues and any reduction and/or disruption of these two proteins may lead to cancer." (PMID 32458652, 2020).
cancer (continued). "A PV, mainly observed in some families from North-Western Sicily (16 individuals, 5 of which cancer patients) belonging to the geographical area that includes the city of Trapani and neighboring areas, is named BRCA2-6310del5 (HGVS nomenclature: c.6082_6086del; p.Glu2028fs)." (PMID 32380732, 2020). "Family-based studies including a multifactorial model of pathology, a cosegregation profile, and the cooccurrence and family history of cancer may exemplify the most reliable methods for classifying BRCA2 gene variants." (PMID 32444794, 2020). "BRCA2 interacts with the RAD51 protein, which catalyzes homologous DNA pairing and DNA strand exchange, and overexpression of BRCA2 and RAD51 is associated with poor prognosis in human cancer." (PMID 32005245, 2020). "Moreover, HPV proteins, especially E6 and E7, are able to interact with breast and ovarian cancer susceptibility gene-1 (BRCA1) and BRCA2 that are tumor suppressors agents." (PMID 32458652, 2020). "In order to develop assays for functional characterization of cancer-associated variants located in BRCA1 and BRCA2, yeast strains overexpressing full length BRCA1 or BRCA2 under the control of a constitutive (pADH) or inducible promoter (pGAL1) have been constructed." (PMID 32656256, 2020). "Importantly, the HR gene RAD52 has been found to be synthetically lethal to the tumor suppressor gene BRCA2; this represents an important finding to design more precise cancer therapies." (PMID 32656256, 2020). "Interestingly, several of the human cancer predisposition genes have been discovered in the constitutional (germline) DNA of dogs with cancer, including mutations in BRCA1, BRCA2, and p5321–24." (PMID 32005926, 2020). "This suggests that guidelines such as NCCN may exclude from testing a significant number of women with mutations in cancer predisposition genes other than BRCA1 and BRCA2." (PMID 31963545, 2020). "The results of our study suggest that BRCA1 (but not BRCA2)-mutated women with no history of cancer have an independent reduction in the response to ovarian stimulation." (PMID 31872386, 2020). "Furthermore, we characterize the penetrance of cancer in carriers of pathogenic BRCA1 and BRCA2 variants." (PMID 33087929, 2020). "Among the 481 female patients, 135 patients were detected to carry pathogenic (P)/likely pathogenic (LP) mutations (28.1%), which corresponded to 12 different cancer predisposition genes [14.6% (70/481) on BRCA1 gene, 5.0% (24/481) on BRCA2 gene, 8.5% (41/481) on non‐BRCA1/2 genes]." (PMID 30982232, 2019). "The multivariable analysis also showed a significant age-dependent decrease in risk of recurrence and cancer-related death in non-carriers but not in BRCA1/BRCA2 carriers." (PMID 31141992, 2019). "Other notable mutated cancer genes were BRCA2, NF1, and GATA3, each occurring once in non-overlapping tumors." (PMID 31618954, 2019). "Twenty-two BRCA1 and BRCA2 germline variants were identified in 12 different cancer types, of which 10 (45%) were not previously identified in these patients based on the current clinical guidelines." (PMID 31263571, 2019). "Here, we have undertaken this approach for BRCA1 and BRCA2 in 28 cancer types." (PMID 31360904, 2019). "It should be noted that patients from Group 4 were not tested for germline mutations in BRCA1/BRCA2 because of the criteria adopted by the Oncogenetics Department of Barretos Cancer Hospital." (PMID 31244284, 2019). "The cancer types commonly considered important for risk assessment are breast (female and male), ovarian, prostate, and pancreatic cancer, all of which are included in the BOADICEA model predicting risk of cancer for BRCA1 and BRCA2 pathogenic variant carriers." (PMID 31131967, 2019).
cancer (continued). "Given that Brca2 is a well-established cancer-suppressor gene, we can speculate on the potential contribution of Meilb2 to cancer development." (PMID 30760716, 2019). "Similarly, a BRCA2-mimetic cell-penetrating peptide disrupting BRCA2-RAD51 interaction conferred PARPi sensitivity in cancer cell lines." (PMID 31921645, 2019). "Our findings help to explain the association of this variant with a lower cancer risk in BRCA2 mutation carriers and highlight the importance of genetic changes in BER pathway genes as modifiers of cancer susceptibility for BRCA1 and BRCA2 mutation carriers." (PMID 30747491, 2019). "Therefore, analysis of only BRCA1 and BRCA2 would explain the genetic etiology of cancer in just 10.5% (126/1197) of the individuals in our cohort." (PMID 31159747, 2019). "Pathogenic variants in BRCA1 and BRCA2 (BRCA1/2) lead to increased risk of breast, ovarian, and other cancers, but most variant-positive individuals in the general population are unaware of their risk, and little is known about prevalence in non-European populations." (PMID 31892343, 2019). "Despite these findings, aneuploidy is not more prevalent in BRCA2-associated versus non-BRCA2-associated human cancers." (PMID 30930946, 2019). "By increasing uptake of BSO and breast MRI, cancer incidence and mortality in women with a BRCA1 or BRCA2 mutation could be reduced." (PMID 30971774, 2019). "Indeed, PARP inhibition in BRCA1 or BRCA2‐defective cancer cells leads to increased levels of mitotic aberrancies including chromatin bridges and micronuclei." (PMID 31529615, 2019). "All BRCA frameshift and stop-gain variants, except those after p.3325 in BRCA2, were designated pathogenic mutations; terminal BRCA2 truncating variants do not confer the high cancer risks of other truncating mutations." (PMID 31360904, 2019). "Our results provide also the first pre-clinical evidence that certain 6-TG analogues, namely 2-N-6-BP and 2,6-DTP, may be effective for treatment of BRCA2-proficient cancers." (PMID 31284411, 2019). "BRCA2, BLM, ERCC2, RECQL, REV3L and RIF1 were among the most promising candidates, with some of them previously associated with predisposition syndromes to other cancers." (PMID 30871259, 2019). "Our observations of TNFα sensitivity of BRCA2-defective cancer cells suggest that BRCA2 mutant tumors may be selectively sensitive to TNFα." (PMID 30626869, 2019). "These are representative known cancer predisposition genes: BRCA1, BRCA2, KRAS and RET." (PMID 31391007, 2019). "How can BRCA1 and BRCA2 gene testing in patients with cancer be increased?" (PMID 31125106, 2019). "Approximately 15–20% of HGSOCs may be inherited with the most common germline mutations related to alterations in breast cancer 1 (BRCA1) and breast cancer 2 (BRCA2) genes." (PMID 30909618, 2019). "Since TPX2 depletion preferentially affects cell survival in BRCA2-depleted cancer cells and because TPX2 functions in mitotic spindle assembly, we examined whether progression through mitosis is aberrant in BRCA2-deficient cells." (PMID 30177840, 2019). "The constitutively higher levels of ROS in cancer cells compared with normal cells may be one of the factor cooperating with BRCA2 signaling in promoting 6-TG-mediated apoptosis in cancer cells." (PMID 31284411, 2019). "More puzzlingly, diploidy in BRCA2-associated cancers is a negative prognostic factor, unlike non-BRCA2-associated cancers and many other human cancers." (PMID 30930946, 2019).
cancer (continued). "CRRM might be recommended for BRCA1 cancers, while BRCA2 cancers may avoid CRRM through the use of thorough MRI surveillance and improvements in the indication and the technical skills required in MRI-guided biopsy." (PMID 30820924, 2019). "Since Aurora kinase A, which is associated with TPX2, is currently tested as a therapeutic target in cancer treatment, we investigated whether BRCA2-mutant cancer cells were more sensitive to chemical inhibition of Aurora-A." (PMID 30177840, 2019). "Notably, CDK1 inhibition significantly reduced the levels of genomic instability, underlining that premature entry induced by ATR inhibition drives genomic instability in PARP inhibitor‐treated BRCA2‐depleted cancer cells." (PMID 31529615, 2019). "Data from the Oncogenetics and Cancer Prevention Unit of the Oncology Service at the Geneva University Hospitals was merged with the Geneva Cancer Registry data to identify women who underwent counselling and were tested for BRCA1 or BRCA2 germline pathogenic variants." (PMID 31491032, 2019). "Importantly, as our patient’s phenotype is most probably a consequence of the BRCA2 p.Pro2767Ser variant, the latter should be included in the genetic testing of HBOC patients and their relatives, to assess their cancer risk." (PMID 31569370, 2019). "Notably, the knowledge of a BRCA1/BRCA2 mutation is likely to significantly change the assessment of a DCIS patient's risks for future cancers and the cancer prevention/risk reduction recommendations that would be considered." (PMID 30652428, 2019). "Instead, diploid and aneuploid cancers occurred in roughly equal proportions in BRCA2 mutation carriers and noncarriers." (PMID 30930946, 2019). "In the breast, as well as all other tissues, the BRCA1 and BRCA2 are expressed and involved in repair process of damaged DNA and any reduction or disruption of these two proteins could lead to cancer." (PMID 30642295, 2019). "Although they were not sequenced for BRCA1 and BRCA2 mutations, their advanced age and the lack of a family history of cancer make them unlikely to be mutation carriers." (PMID 29433565, 2018). "Interestingly, our study emerged that in BRCA1-mutated OC the expression of BRCA1-transcripts was lower, but in contrary those of BRCA2 were significantly higher as compared withBRCA1-wildtype cancers." (PMID 30111871, 2018). "So far, a number of gene- or protein-based cancer biomarkers have been applied to the clinical management of cancer patients with BRCA1/BRCA2 (breast/ovarian cancer), HER-2 (breast cancer), PSA (prostate cancer), and S100 (melanoma) as a few representative examples." (PMID 29527514, 2018). "By contrast, in cells lacking a BRCA2 carboxyl (C)-terminal region targeted by cancer-causing mutations, damage-induced RAD51 assemblies initiate but do not extend into filaments." (PMID 29309696, 2018). "A recent study showed that the cancer risk of pathogenic variant carriers in the different regions of BRCA2 is not similar." (PMID 29707112, 2018). "Future prospective studies are needed to determine whether the same psychosocial factors influence the surgical decision making of individuals with hereditary cancer predispositions beyond BRCA1 and BRCA2." (PMID 29733510, 2018). "The non-standard decision made by the Senior Underwriter and Chief Medical Officer for a 24-year old female non-smoker positive for the BRCA2 gene variant who applied for DI was cover with exclusion of a claim for any cancer." (PMID 29891881, 2018). "Mutations of BRCA1 and BRCA2 genes considerably increase an individual’s risk of OC;7 combined with non-genetic information (eg, family history of cancer, age and lifestyle factors), this genetic information can be used to estimate a woman’s risk." (PMID 30021754, 2018). "In the Italian muticentre HIBCRIT-1 screening study, mammography did not significantly increase cancer detection rates compared to MRI alone for either BRCA1 or BRCA2 mutation carriers." (PMID 30513626, 2018).